SLC31A1 (solute carrier family 31 member 1)
Description:
[High affinity copper uptake protein 1]: Uniporter that mediates the transport of copper(1+) from the extracellular space to the cytoplasm, across the plasma membrane and delivers directly copper(1+) to specific chaperone such as ATOX1, via a copper(1+)- mediated transient interaction between the C-terminal domain and a copper(1+) chaperone, thus controlling intracellular copper(1+) levels. May function in copper(1+) import from the apical membrane thus may drive intestinal copper absorption (By similarity). The copper(1+) transport mechanism is sodium-independent, saturable and of high-affinity. Also mediates the uptake of silver(1+). May function in the influx of the platinum-containing chemotherapeutic agents. The platinum-containing chemotherapeutic agents uptake is saturable (By similarity). In vitro, mediates the transport of cadmium(2+) into cells. Also participates in the first step of copper(2+) acquisition by cells through a direct transfer of copper(2+) from copper(2+) carriers in blood, such as ALB to the N-terminal domain of SLC31A1, leading to copper(2+) reduction and probably followed by copper(1+) stabilization. In addition, functions as a redox sensor to promote angiogenesis in endothelial cells, in a copper(1+) transport independent manner, by transmitting the VEGF-induced ROS signal through a sulfenylation at Cys-189 leadin g to a subsequent disulfide bond formation between SLC31A1 and KDR. The SLC31A1-KDR complex is then co-internalized to early endosomes, driving a sustained VEGFR2 signaling. [Truncated CTR1 form]: Mobilizes copper(1+) out of the endosomal compartment, making copper(1+) available for export out of the cells.
Synonyms: hCTR1; COPT1; CTR1; NSCT
Tractability: Antibody: UniProt places it where antibodies can reach, with high confidence; its Gene Ontology location is reachable by antibodies, with high confidence; UniProt predicts a signal peptide or a membrane-spanning region. PROTAC: ubiquitination databases record sites on it.
Safety:
Unwanted effects reported when the protein is acted on. In parentheses: how it was acted on, where the effect was seen, and who reports it.
drug toxicity (source: ClinPGx)
drug toxicity and hematologic toxicity (source: ClinPGx)
hematologic toxicity (source: ClinPGx)
overall survival (source: ClinPGx)
severe ototoxicity (source: ClinPGx)
Gene: Protein-coding gene on chromosome 9 (113,221,191 to 113,264,492, forward strand). Ensembl gene ENSG00000136868.
Subcellular location: Cell membrane; Early endosome membrane; Recycling endosome membrane; Apical cell membrane; Late endosome membrane; Basolateral cell membrane
Pathways (Reactome):
Transport of small molecules: Metal ion SLC transporters
Gene Ontology:
Molecular function: copper ion binding; copper ion transmembrane transporter activity; identical protein binding; protein binding; silver ion transmembrane transporter activity; xenobiotic transmembrane transporter activity
Biological process: angiogenesis; copper ion import; plasma membrane copper ion transport; protein complex oligomerization; silver ion transmembrane transport; vascular endothelial growth factor receptor-2 signaling pathway; xenobiotic transport; copper ion transport; metal ion transport; copper ion transmembrane transport
Cellular component: early endosome membrane; plasma membrane; recycling endosome membrane; apical plasma membrane; basolateral plasma membrane; late endosome membrane; intercalated disc; late endosome; membrane; recycling endosome
Genetic constraint (gnomAD): Loss-of-function variants: 5 observed, 17.94 expected, observed/expected ratio (o/e) 0.28, 90% interval 0.14 to 0.59. The upper end of that interval is the gene's LOEUF score, 0.59, which puts it in group 2 of 6, group 1 being the genes least tolerant of losing a copy. Missense variants: 161 observed, 253.08 expected, observed/expected ratio (o/e) 0.64, 90% interval 0.56 to 0.73. Synonymous variants: 76 observed, 81.8 expected, observed/expected ratio (o/e) 0.93, 90% interval 0.77 to 1.12.
Homologues: Orthologues: chimpanzee SLC31A1 (100% identical), macaque SLC31A1 (99% identical), guinea pig SLC31A1 (93% identical), dog SLC31A1 (93% identical), mouse Slc31a1 (93% identical), rabbit SLC31A1 (90% identical), rat Slc31a1 (89% identical), pig SLC31A1 (88% identical), zebrafish slc31a1 (71% identical), tropical clawed frog slc31a1 (60% identical), Caenorhabditis elegans F58G6.3 (22% identical), Caenorhabditis elegans K12C11.3 (18% identical), and 2 more. Paralogues in human: SLC31A2 (21% identical).
Diseases named in the same sentence as SLC31A1 in open-access papers:
SLC31A1 is named in the same sentence as 117 diseases in open-access papers, as found by Europe PMC text mining. Sharing a sentence is not in itself a finding about the gene and the disease. The quoted sentences say what the papers report.
breast cancer (31 papers, 2016 to 2026). A primary or metastatic malignant neoplasm involving the breast. "Utilizing a database, researchers identified solute carrier family 31 member 1 (SLC31A1) as a potential cuproptosis‐related gene that is upregulated in breast cancer and is linked to poor patient prognosis." (PMID 39290254, 2024). "Since cuproptosis-related gene SLC31A1 was highly expressed and served as a promising diagnostic and prognostic marker in breast cancer, it is necessary to evaluate the role of SLC31A1 in predicting chemotherapeutic response during breast cancer treatment." (PMID 37884650, 2023). "Using R language and multiple network databases, expression levels, prognostic and diagnostic values of cuproptosis-related gene SLC31A1 were analyzed in breast cancer." (PMID 37884650, 2023). "Results revealed that the SLC31A1 expression was significantly positively associated with all m6A-related genes in breast cancer." (PMID 37275369, 2023). "More recently, SLC31A1, a cuproptosis‐related gene, has emerged as a novel breast cancer biomarker with diagnostic and prognostic significance, showing strong upregulation driven by hypomethylation and association with poor survival and immune cell infiltration." (PMID 41523619, 2025). "Specifically, AUC of 1 year, 5 year, and 15 year was 0.542, 0.574, and 0.666, indicating that SLC31A1 might also be a promising diagnostic marker in breast cancer." (PMID 37884650, 2023). "In order to further evaluate the diagnostic value of cuproptosis-related gene SLC31A1 in breast cancer, ROC curve of SLC31A1 was drawn by using the survival package and timeROC package in R language based on breast cancer samples and normal breast tissues from TCGA." (PMID 37884650, 2023). "At present, SLC31A1 might be a promising diagnostic/prognostic biomarker in breast cancer; it has also been found to modulate chemotherapeutic sensitivity in other cancers." (PMID 36902801, 2023). "Based on our analysis, future studies may focus on the underlining mechanism of SLC31A1 regulating CAF in luminal A breast cancer." (PMID 37275369, 2023). "To further assess whether SLC31A1 is related to m6A modification, we assessed the association between the expression of SLC31A1 and 20 m6A-related genes in breast cancer." (PMID 37275369, 2023). "Furthermore, our study showed that low levels of SLC31A1 in breast cancer were associated with favorable clinical outcomes, which is probably through copper depletion." (PMID 35996075, 2022). "Whether the accumulation of intracellular copper with high levels of SLC31A1 caused proteotoxic stress and cell death in breast cancer remains to be validated." (PMID 35996075, 2022). "Thus, CDKN2A and SLC31A1 may be two most potential genes associated with cuproptosis in breast cancer." (PMID 37884650, 2023). "YTHDF3 interacts with solute carrier family 31 member 1 (SLC31A1) to co‐regulate citrate synthesis in breast cancer." (PMID 40923717, 2026). "Baseline tumor SLC31A1 gene expression was analyzed in a retrospective cohort of 1,632 neoadjuvant-treated breast cancer patients, who were subsequently stratified by pathologic response across molecular subtypes and tumor grades." (PMID 42268797, 2026). "We identified 13 members of the copper transport system associated with the occurrence, progression, and mortality of breast cancer, including SLC31A1, DMT1, ATP7A, ATP7B, MTs, GSH, ATOX1, CCS, COX17, SCO1, SCO2, and COX11." (PMID 39676279, 2024). "Overactivation of SLC31A1 can also induce DNA damage and death in breast cancer cells by increasing intracellular copper ions and ROS." (PMID 39676279, 2024). "Data from the Human Protein Atlas (HPA) further demonstrate that SLC31A1 expression is notably lower in normal breast tissue compared to breast cancer tissue." (PMID 39702350, 2024). "Overexpression of SLC31A1 can significantly enhance the anticancer effect of copper or copper complex [CuCl2 (impy)] as a breast cancer therapeutic agent and inhibit breast cancer survival." (PMID 39676279, 2024).
breast cancer (continued). "SLC31A1 in the breast cancer tissues was upregulated and indicated poor prognosis, immune cell infiltration, and chemosensitivity." (PMID 39325172, 2024). "We evidenced through a series of crucial in vivo and in vitro investigations that SLC31A1 has a significant impact on the promotion of Her2 + enriched breast cancer cells." (PMID 39448672, 2024). "An analysis of the Molecular Taxonomy of Breast Cancer International Consortium (METABRIC) 2000 dataset showed that patients with breast cancer with a high expression of the CRG SLC31A1 had a worse prognosis than those with a low expression of this CRG." (PMID 38732186, 2024). "For instance, the SLC31A1-related axis in breast cancer and the role of specific lncRNAs in LAUD have shown promising results in predicting patient outcomes and guiding therapeutic strategies." (PMID 39325172, 2024). "As the upstream of SLC31A1, AMPK and its agonist metformin can significantly improve SLC31A1 level by influencing Nedd4l interaction, which can be used in conjunction with metformin and copper chelating agent for breast cancer treatment." (PMID 39676279, 2024). "The star gene of cuproptosis, SLC31A1, is upregulated in breast cancer and can act as a sentinel for poor prognosis in breast cancer patients." (PMID 39676279, 2024). "Research has shown that SLC31A1 expression is significantly elevated in breast cancer (BRCA), correlating with a poorer overall survival rate." (PMID 39702350, 2024). "The hsa-miR-29c-3p-SLC31A1 axis was considered as the potential pathway involved in the progression of breast cancer by regulating copper transport." (PMID 37275369, 2023). "SLC31A1 expression was found to be elevated in cervical, endometrial, and breast cancers compared to that in normal tissues, but reduced in clear cell renal cell carcinoma, liver hepatocellular carcinoma, and lung adenocarcinoma." (PMID 37853210, 2023). "SLC31A1 was a potential cuproptosis-related gene in breast cancer, which was significantly upregulated and was able to predict diagnosis, prognosis, chemosensitivity, and immune infiltration." (PMID 37884650, 2023). "Recently, two pieces of research also demonstrated that SLC31A1-dependent copper absorption increases the malignancy grade of pancreatic and breast cancers." (PMID 37113755, 2023). "The results showed that the expression of SLC31A1 was significantly positively correlated with immune markers in breast cancer, especially for STAT3 of Th17 (r = 0.382, p < 0.001), STAT1 of Th1 (r = 0.358, p < 0.001), and CCR8 of Treg (r = 0.304, p < 0.001)." (PMID 37275369, 2023). "Our study suggested that SLC31A1 mRNA was over-expressed in breast tumor tissue and breast cancer cell lines, and which was closely related to poor relapse-free survival (RFS) and distant metastasis-free survival (DMFS)." (PMID 37275369, 2023). "After analyzing and confirming their prognostic values in breast cancer, SLC31A1 was selected as the most potential gene responsible for cuproptosis." (PMID 37884650, 2023). "According to the ROC curve, SLC31A1 displayed the ability to distinguish breast cancer samples from normal breast tissues, and the AUC value increased with the prolongation of follow-up time." (PMID 37884650, 2023). "Combined with these results, hsa-miR-29c-3p was identified to be the most potential miRNA regulating SLC31A1 in breast cancer." (PMID 37275369, 2023). "The results showed that breast cancer patients with high expression of SLC31A1 had a poor relapse free survival and distant metastasis free survival." (PMID 37884650, 2023). "The result revealed that the mRNA expression level of SLC31A1 was higher in breast cancer tissues than in normal breast tissues." (PMID 37275369, 2023). "In our study, the correlation between the SLC31A1 expression and clinicopathological characteristics in breast cancer patients based on the TCGA database was analyzed." (PMID 37275369, 2023).
breast cancer (continued). "Given that no relevant reports on miR-204-5p and SLC31A1 are currently available, future studies investigating the regulation of miR-204-5p in SLC31A1 are needed in different breast cancer subtypes with distinctly different biology." (PMID 37884650, 2023). "SLC31A1 was negatively related to a favorable outcome in breast cancer, and the AUC value increased with the prolongation of follow-up time." (PMID 37884650, 2023). "The results showed that only CDKN2A and SLC31A1 were significantly increased in breast cancer samples than those in normal tissues." (PMID 37884650, 2023). "By using R language and multiple online databases on 17 candidate cuproptosis-related genes, CDKN2A and SLC31A1 were found to be increased in breast cancer samples with respect to normal tissues." (PMID 37884650, 2023). "First, while most of the publications reporting SLC31A1 were based on limited data derived from online tools, the current work utilized R language to obtain TCGA breast cancer information in a more synchronous and comprehensive manner." (PMID 37884650, 2023). "This study analyzed the expression and prognostic value of SLC31A1 in breast cancer and constructed a ceRNA regulatory network." (PMID 37275369, 2023). "We found that the expression of SLC31A1 mRNA was upregulated in breast cancer tissues and breast cancer cell lines." (PMID 37275369, 2023). "For instance, High expression of SLC31A1 is correlated with poor prognosis and dysregulated immune cell infiltration in breast cancer." (PMID 38114959, 2023). "It is reported that SLC31A1 correlated to Wilson disease, Parkinson's disease, lung and breast cancer 37-40, making it a potential predictor for diagnosis, prognosis and therapeutic target." (PMID 37324184, 2023). "We identified the LINC00511/miR-29c-3p axis as the upstream regulatory mechanism of SLC31A1 in breast cancer." (PMID 37275369, 2023). "In this study, we predicted the regulation of non-coding RNA (ncRNA) related to SLC31A1 in breast cancer and attempted to construct a ceRNA network." (PMID 37275369, 2023). "We examined the expression of SLC31A1 mRNA in breast cancer tissues and cell lines using Real-time PCR." (PMID 37275369, 2023). "Further subgroup analysis showed that the expression level of SLC31A1 in breast cancer tissues of all subtypes (luminal, HER2 positive, and triple negative) was higher than that in normal breast tissues." (PMID 37275369, 2023). "Combined with the expression analysis, survival analysis, and correlation analysis, LINC00511 was considered the most significant lncRNA upstream of the hsa-miR-29c-3p/SLC31A1 axis in breast cancer." (PMID 37275369, 2023). "With a better understanding of copper homeostasis, SLC31A1 exhibits a promising biomarker for drug sensitivity and a novel therapeutic target for overcoming drug resistance in breast cancer." (PMID 35996075, 2022). "The expression levels of SLC31A1 of breast cancer samples were significantly higher than those of normal samples." (PMID 35996075, 2022). "We next conducted univariate and multivariate Cox regression analyses to examine the independent prognostic role of SLC31A1 in breast cancer with other clinical characteristics, including age, T-stage, N-stage and clinical stage." (PMID 35996075, 2022). "Our pan-cancer expression analysis results also showed that SLC31A1 was upregulated in breast cancer samples, while downregulated in kidney and lung cancer samples." (PMID 35996075, 2022). "Next, we developed a nomogram based on SLC31A1 expression, age, T-, N-stage and clinical stage to predict the 1-, 3-, 5- and 10-year overall survival (OS) of patients with breast cancer." (PMID 35996075, 2022). "SLC31A1 overexpression led to an increase in copper uptake in breast cancer cells and xenograft models." (PMID 35996075, 2022). "The expression level of SLC31A1 was found to be higher in the breast cancer samples compared with normal tissues." (PMID 35996075, 2022).